CD4 (CD4 molecule)
Diseases named in the same sentence as CD4 in open-access papers (continued):
Sharing a sentence is not in itself a finding about the gene and the disease.
tumor (continued). "The observed higher numbers of tumor infiltrating CD4 cells indicate their role in keeping tumor associated CMV reactivation in check." (PMID 40676060, 2025). "Among 35 tumors obtained from patients with EGFR-mutated NSCLC treated with EGFR-TKIs, the present tumor showed relatively increased inflammatory cells, including exhausted CD4 and CD8 positive cells and M1-like macrophages, compared to other tumors." (PMID 41001033, 2025). "Second, MET played an important role in regulating the function of dendritic cells, which were responsible for presenting tumor-associated antigens and activating regulatory CD4+ T cells that control cytotoxic CD8+ T cells." (PMID 40330151, 2025). "In both models, anti-CD4 antibody treatment was associated with a trend toward tumor reduction; however, statistical significance was reached only in the mock group, possibly due to inter-animal biological and experimental variability in the ULBP2 group." (PMID 40558520, 2025). "CD163+ M2 tumor–associated macrophages (TAMs) predominated, whereas CD4+ and CD8+ T cells were scarce, indicating an immune-suppressive microenvironment." (PMID 40469416, 2025). "Research evidence suggested that dysregulation of cholesterol metabolism in tumor cells directly impairs the function of immune cells: CD8+ T cells are more susceptible to cholesterol deficiency than CD4+ T cells." (PMID 41174058, 2025). "Multiplex immunohistochemical staining (GPC3, CD4, Foxp3) revealed distinct tumor immune microenvironments between risk groups." (PMID 40533802, 2025). "CD4+ Th17 subset has been associated with tumor progression by inducing IL-17-mediated angiogenesis, suppressing CD8+ TILs, and thereby promoting a worse prognosis." (PMID 41425582, 2025). "The morphologic hallmark of AITL is striking arborized vascularity caused by a CD4+ T follicular helper tumor cell clone in orchestration with a robust microenvironment." (PMID 41303704, 2025). "At the same time, CD4+ T cells can activate antigen-presenting cells through CD40-CD40L pathway to enhance the antigen presentation of tumor-associated antigens." (PMID 40176817, 2025). "In this work, orthotopic transplantation of PyMT tumor cells demonstrated that SF-RON loss increased TCF1+ CD4+ T-cells in metastatic lesions, which prevented outgrowth as well as an increase in the CD8+ T-cells which mediated the killing of metastatic cells." (PMID 40282397, 2025). "The immunomodulatory capacity of PTSO, demonstrated both in vitro and in vivo, was also linked to a notable increase in anti-tumor effector immune cells, particularly CD4+ and CD8+ T lymphocytes and NK cells." (PMID 41010517, 2025). "A recent study integrating TME characterization via imaging mass cytometry (IMC) with whole genome sequencing data reported an inverse correlation between macrophage infiltration, CD4+ T-cell abundance, and tumor mutational burden (TMB)." (PMID 41463268, 2025). "Several studies have observed the activation of CD8+ and CD4+ T cells when exposed to DCs exosomes associated with the induction of an anti-tumor immune response in vivo through exosomal CD80 and endogenous IL-2." (PMID 40141358, 2025). "Tumor regression in these models was associated with a marked reduction in CD4+ Treg cells and exhausted CD8+ T cells, alongside expansion of activated cytotoxic CD8+ T cells." (PMID 40723208, 2025). "Simultaneously, imiquimod causes peripheral lymphocytes to express CXCR3, a homologous chemokine receptor that causes CD4+ T cells to infiltrate and accumulate within the tumor and is crucial for tumor rejection." (PMID 40727443, 2025). "In this context, immunogenicity refers to the capacity of a tumor-associated protein to elicit adaptive immune responses, including antibody production and activation of CD4+ and CD8+ T cells in cancer patients." (PMID 41345672, 2025). "To characterize the immunological mechanism underlying this protection, we analyzed CD4+ tumor-infiltrating lymphocytes (TILs)." (PMID 41441899, 2025).
tumor (continued). "The fibrotic microenvironment rich in IL6+CAFs was associated with decreased high intratumoral CD8+ and CD4+TILs, which normally exert an anti-tumor effect, and was hence correlated with a poorer prognosis." (PMID 40227764, 2025). "In the case of canine histiocytomas, spontaneous tumor regression has been associated with progressive infiltration by lymphocytes (CD4+, CD8+, CD3+) and myelocytic or histiocytic cells." (PMID 40725420, 2025). "Intriguingly, increased levels of regulatory T cells, natural killer T cells, natural killer cells, and central memory CD4+ T cells, were higher in the high-risk patients, suggesting enhanced immunological activity and indicating “hot” tumor phenotypes." (PMID 40963631, 2025). "A preponderance of reports document an activated T-helper 1 (TH1) phenotype of cytotoxic CD4+ T cells, including tumor microenvironment (TME)-associated ones, while alternate polarization patterns have been observed." (PMID 41030456, 2025). "The ratio of intra- to extra-tumoral locations of immune cells was significantly higher in mutated tumours, especially for CD4, CD8 and FOXP3 lymphocytes." (PMID 40427006, 2025). "Mutations within PAPPA2 have been associated with higher levels of CD4 memory cells and lower levels of Treg cells, suggestive that it limits tumor growth in humans." (PMID 40822650, 2025). "CD320 was found to be positively associated with tumor microenvironment-forming cells (B cells, CD4+ T cells, macrophages, and dendritic cells)." (PMID 40565117, 2025). "By conducting Cox univariate analysis on clinical-pathology-immune factors, we identified the presence of MVI, incomplete tumor capsule, and low CD4+ T cell infiltration in the CT region as risk factors which decreased RFS." (PMID 41212769, 2025). "Prior animal studies have shown that NYT decreases CD4+ T-cell levels in tumor models, and miR-16 has been implicated in regulating CD4+NKG2D+ activity by directly targeting NKG2D." (PMID 41597334, 2025). "Studies have shown that the HLA-DR marker presents tumor-associated antigens (TAAs) that are recognized by CD4+ T cells, which then produce cytokines to inhibit tumor growth." (PMID 39941799, 2025). "Meanwhile, tumor-promoting cells, such as naive CD4+ T cells, macrophage Mo cells, activated mast cells, and resting CD4+ T cells were highly infiltrated in the high-risk group." (PMID 40145017, 2025). "FRC-like were enriched in immune-hot HPV+ve tumours, associated with CD4 + T-cells and B-cells in tertiary lymphoid structures and regulated through non-canonical NF-κB signalling via lymphotoxin." (PMID 39757146, 2025). "Particularly, in HNSCC, the enhanced expression of PD-L1 in the TME, not only on tumor cells but also in M2-macrophages, was associated with decreased levels of effector CD4+ and CD8+ cells." (PMID 40650111, 2025). "CCL11 was shown to increase the CD4+CD25+Foxp3+ Tregcells proportion, CCR3 and Foxp3 expression, and the release of IL-2 andtransforming growth factor (TGF) β1 in non-tumor-associated CD4+ T cells through the STAT5 signalingpathway." (PMID 40026499, 2025). "The density of CD4+/CD8+ T cell infiltration in the tumor stroma is strongly associated with NSCLC patient prognosis, with higher TIL levels correlating with improved overall survival (OS) and disease-free survival (DFS)." (PMID 40787464, 2025). "There is growing recognition that a subset of tumors express MHC class II (MHCII), causing recognition of antigens by TCRs of CD4+ T-cells that contribute to the anti-tumor response." (PMID 40828595, 2025). "Our study revealed that the risk score was predictive for unsuccessful anti-tumor immune response stages, encompassing the liberation of cancer cell antigens, initiation and activation processes, and recruitment of CD4 and CD8 T cells." (PMID 39574472, 2024).
tumor (continued). "A groundbreaking study from Devalaraja and colleagues provided a unifying theory by showing that tumor-expressed ALDH1a3 generates retinoic acid as a paracrine factor to activate tumor-associated macrophages and suppress CD4 T cell activity." (PMID 39133222, 2024). "Previous studies have highlighted that higher levels of CD8+ T cells, CD4+ T cells, and PD‐L1 in tumor tissues are associated with a favorable response to immunotherapy." (PMID 39275896, 2024). "As fibroblast-specific deletion of Ccn1 resulted in impaired collagen organization and neovascularization, we reasoned that CCN1-deficient stroma would enhance the ability of CD4+ T cells to penetrate tumor cells." (PMID 38363129, 2024). "Low tumor-infiltrating T lymphocytes and a high CD4/CD8 ratio were associated with shorter survival in patients with DLBCL, indicating the crucial role of CD8+ T cells in the TME of DLBCL." (PMID 39057061, 2024). "Abundant evidence suggests that an increased presence of endogenous FOXP3+ CD25+ CD4+ Treg cells in tumor tissues is associated with poor prognosis." (PMID 39668835, 2024). "Previous studies have shown that CD8A and CD4 are associated with the presence of CD8+ T cells and CD4+ T cells, respectively, both of which can exert anti‐tumour effects and indicate a better immune therapy response." (PMID 38946232, 2024). "In the case of GBM, there is a phenomenon of so-called Th “exhaustion” (progressive loss of function), presumably diminishing the anti-tumor activity of the mixed population of CD4+ T cells." (PMID 38786032, 2024). "The synergetic effect of both POLE-mutation-induced and PDT-induced tumor-antigen release would effectively activate the immune cells like CD4+ T cells, CD8+ T cells, and NK cells." (PMID 39007151, 2024). "Further, one of the CD4+ T cell clusters was negatively associated with CD4+ T cell infiltration in the tumor." (PMID 38653982, 2024). "The bar graph demonstrated that high-risk patients had more immune cell infiltration within the tumor tissue, including activated B cells, activated CD4 T cells, activated CD8 T cells, activated dendritic cells, and so on." (PMID 38644411, 2024). "These signals enhance the frequency of immunosuppressive cells with protumor function, including regulatory CD4+ T cells and tumor-associated macrophages." (PMID 38903501, 2024). "HP1γ negatively correlated with the levels of B cells, CD8+ and CD4+ T cells, macrophages, neutrophils, and dendritic cells.HP1γ positively correlated with tumor mutation burden, neoantigen count, and PD-1, PD-L1, and PD-L2 levels." (PMID 39519018, 2024). "The two groups exhibited distinct immune responses, with CD4 memory‐resting T cells being highly expressed in the low‐risk group, suggesting a potentially beneficial role in inhibiting tumour growth." (PMID 39031800, 2024). "The biological activity of B7-H4 is associated with a reduced inflammatory CD4 T cell response, and the correlation between tumor-associated macrophages expressing B7-H4 and regulatory T cells (Tregs) expressing FoxP3 in the tumor microenvironment." (PMID 38612764, 2024). "The differentiation of naive CD4+ T cells into peripheral Treg cells is also modulated by tumor-associated macrophages (TAMs) through the expression of some cytokines, including CXCL1." (PMID 38892411, 2024). "The composition of immune cells in PDAC tumor microenvironment is diverse, including CD4+ T cells, CD8+ T cells, cancer associated fibroblast cells, and different kinds of macrophages." (PMID 38189855, 2024). "This study revealed that ER expression is linked to a reduction in tumor-infiltrating lymphocytes (TILs), especially CD4+ T cells." (PMID 39682229, 2024). "Earlier experiments have demonstrated the significant role of PD-L1 as a tumor or antigen-presenting cell-associated negative regulator of CD4+ T cell responses." (PMID 38745661, 2024).
tumor (continued). "The expression levels of CD4+ T cells, monocytes, dendritic cells, B cells, Th1 cells, Th2 cells, and Tumor-infiltrating lymphocytes (TILs) in the high-risk subgroup were higher than those in the low-risk subgroup." (PMID 38895621, 2024). "Specifically, intra-tumor treatment reduced lung metastasis associated with increased T cell infiltration comprised of CD4+ and CD4+CD8+ double-positive T cells." (PMID 38921005, 2024). "IRPS is linked to an immunosuppressive tumor microenvironment characterized by activating forkhead box P3 (FOXP3+) CD4+ T lymphocytes, which further suppress T-cell functions and promote T-cell exhaustion." (PMID 39593745, 2024). "cDC1 and cDC2 subsets activate anti-tumor immune responses by presenting tumor-associated antigens to CD4 and CD8 T cells." (PMID 39188677, 2024). "This study revealed that activated CD4+ T cells optimize cDC1s for CTL cross-priming to tumor cell-associated antigens by providing not only CD40L but also IFN-I, which act in a nonredundant manner." (PMID 38383773, 2024). "In this context, tumors with moderate to high CD3 and CD8 expression were associated with lower tumor purity scores (P < 0.01) and higher cell fractions of CAFs (P < 0.05), macrophages (P < 0.05), and CD4+ T cells (P < 0.05) as revealed by EPIC analysis." (PMID 39024554, 2024). "In contrast, a significant enrichment of CD4+FOXP3+ regulatory T (Treg) cells is observed within tumor-associated TLS compared to peritumoral ones, suggesting a potential for immune suppression." (PMID 39198425, 2024). "We found that PLIN3 was inversely associated with CD4/CD8 in tumor tissue and knocking-down PLIN3 can reduce intracellular LDs deposits, which was consistent with the previous findings, making us turn to investigate immune checkpoint molecules." (PMID 38554152, 2024). "The results of the bar plots showed that the low-risk group had higher levels of CD4+ T cells, M1 macrophages, and mast cells, which have a tumor-suppressive effect, while the high-risk group had higher levels of M2 macrophages, which promote tumor growth." (PMID 38379084, 2024). "In a mouse tumor, the biased association of CD4 T cells toward blood vessels recalls prior literature in which interactions between different T cell subsets and vasculature dictate trajectories of tumor growth or infection." (PMID 38168288, 2024). "Higher infiltration of PD-L1+ lymphocytes in tumour stroma was associated with higher infiltration levels of CD4+ T cells not only in stroma but in tumour islets as well." (PMID 39409156, 2024). "Having shown that both helper cassettes induce CD4+ T cell responses to at least one of the encoded antigens, we next determined the effect of tumor-unrelated and tumor-related CD4+ T cell help on the induction of CD8+ T cell responses." (PMID 39040850, 2024). "Other cells with a role in immune regulation are CD4+ effector T cells, tumor-associated macrophages (TAMs), myeloid-derived suppressor cells (MDSCs), DCs, NKs, and mast cells." (PMID 39050852, 2024). "Strongly reduced tumor resistance of neoHELP-vaccinated mice caused by CD4+ T cell depletion around the time of MC-38 inoculation indicated that neoantigen-specific CD4+ T cells played a major role in the effector phase of the anti-tumor response." (PMID 39040850, 2024). "A recent study found that tumour‐associated macrophages can drive immune checkpoint blockade resistance through CD4+ T cell suppression via PD‐1/PD‐L1 signalling." (PMID 39448550, 2024). "We found that in 33 cancers, PLOD1 expression was negatively correlated with CD8+ T cells, B cells and CD4+ T cells, among others, and positively correlated with monocytes, macrophages, neutrophils and tumor-associated fibroblasts (CAFs)." (PMID 39767559, 2024). "The immune cell population consists of tumor-associated macrophages (TAMs) as well as CD4+ and CD8+ T-lymphocytes, regulatory T-cells (CD25+) and Natural Killer (NK) cells (CD7+)." (PMID 38817895, 2024).
tumor (continued). "Further analysis of the subsets of CD4+ T cells showed that tumours with higher infiltration levels of PD-L1+ lymphocytes in tumour islets were significantly associated with higher IL-17A+CD4+ T cell infiltration in the same compartment." (PMID 39409156, 2024). "ICB responsiveness is typically linked to tumor types infiltrated by good-prognosis, effector-type CD4+ and CD8+ T cells." (PMID 38349740, 2024). "We, and others, found that an inflammatory, CD4+ T cell-associated tumor microenvironment (TME) is necessary for response to chemotherapy in both mice and patients." (PMID 38350880, 2024). "In general, PANoptosis-related high-risk group had a higher proportion of tumor-promoting immune cells (M2 macrophages and Tregs) and a lower proportion of antitumor immune cells (plasma cells, CD4+ naive cells and activated NK cells)." (PMID 38577605, 2024). "This highlights the mechanism underlying low methylation of FOXP3-TSDR in tumor-infiltrating CD4+ T cells in patients with CRC." (PMID 38331927, 2024). "IgM and IgG antibodies binding to allogeneic tumors enabled tumor-infiltrating DCs to process and present tumor antigens to CD4+ T cells, and this response was abrogated in FcγR-deficient mice." (PMID 38461238, 2024). "Tregs, MDSCs, M2-polarized tumor-associated macrophages, and Th2 CD4+ T cells have been linked to ICIs resistance." (PMID 38903504, 2024). "These nanoparticles can modify CAR-T cells in vivo, regulate CD4+ T cell function, inhibit the expression of tumor-associated immunosuppressive cells, and control the release of immunosuppressive agents like IL-2 and transforming growth factor-β (TGF-β)." (PMID 39397869, 2024). "To assess the extent to which increased T-cells in ATRX-deficient tumor-bearing mice promoted overall survival, we depleted CD4+ and CD8 + T-cells in C57BL/6 immunocompetent hosts bearing CT2A AtrxWT or Atrx KO-B tumors." (PMID 38272925, 2024). "Among TILs, the effector immune cells (CD8+T cells and Th1/CD4 + T cells) are associated with tumor immune elimination, while inhibitory phenotypes, such as CD4 + FoxP3 + T cells (Treg), are associated with tumor progression." (PMID 38397152, 2024). "Melanoma cells expressing MHC-II are susceptible to elimination by tumor-specific cytotoxic CD4+ T cells, leading to tumor regression in an adoptive T cell transfer model." (PMID 39263534, 2024). "Second, CD4+ effector T cells can indirectly kill major histocompatibility complex (MHC)-deficient tumor cells that evade CD8+ T cell targeting, thereby independently eradicating established tumors." (PMID 39483483, 2024). "The tumour immune microenvironment (TIME) was characterised by high CD4, CD8, Foxp3, and PD-L1 levels, associating with better pathological regression (TRS0/1)." (PMID 39164491, 2024). "Drawing a parallel with normal hematopoiesis, supposedly, CD4+ T lymphocytes also influence and modulate the changes caused by tumor cells in the hematopoietic niches in BM." (PMID 38690280, 2024). "CD4+ Tregs are crucial in inflammation-linked diseases, exerting a suppressive impact on inflammatory responses within the tumor microenvironment (TME)." (PMID 39050844, 2024). "These activated and mature innate immune cells process tumor-associated antigens and neoantigens in the tumor to generate tumor-specific CD4+ and CD8+ effector and memory T cells." (PMID 38349406, 2024). "Examination of immune infiltration in cohorts containing both HPV+ and HPV-negative HNSCCs supports the association of higher CD4+ Treg cells in tumor and stromal compartments, with more favorable outcome." (PMID 38675879, 2024). "We further showed that a Zn-deficient diet reduced the PD-1 expression on tumor-infiltrating CD4+, CD8+, and γδ+ T cells in contrast to high Zn intake." (PMID 39247196, 2024). "In HCC, TILs predominantly consist of various immune cells, including CD8+ T cells, CD4+ T cells, Tregs, TAMs, tumor-associated neutrophils, myeloid-derived suppressor cells (MDSCs), and NK cells." (PMID 38426090, 2024).